C3 (complement C3)
Diseases named in the same sentence as C3 in open-access papers (continued):
Sharing a sentence is not in itself a finding about the gene and the disease.
lung carcinoma (continued). "In line with our findings, studies have shown that C3-associated complement system activation triggers processes such as tumorigenesis, EMT, and angiogenesis in cervical and ovarian cancers, while tumor tissue deposition has been observed in glioblastoma and lung cancer." (PMID 40283026, 2025). "In lung cancer, CD4+ T cells present intracellular C3 cleavage by cathepsin and C3a signaling inhibits the production of multiple cytokines by CD4+ T cells, independently of FOXP3+ Tregs." (PMID 40370471, 2025). "On one hand, higher levels of the complement proteins C1QB, C3 and C4BPA were detected in plasma from patients with lung cancer than in healthy subjects." (PMID 30841875, 2019). "On the other hand, lower levels of the C1QB, C3 and C4BPA proteins have been detected in lung cancer tissues than in normal lung tissues." (PMID 30841875, 2019). "Using WT and C3-/- mice the study revealed elevated levels of C3a in mice with lung cancer and restriction or even complete absence of tumour growth." (PMID 38178176, 2024). "The results of immunohistochemical analysis showed that compared with the stage I lung cancer group, the expression levels of COPG2IT1 and HLA.DQA1 in the stage III lung cancer group were significantly increased, and the expression levels of LYN, C3 and TNFRSF17 were significantly decreased." (PMID 33215029, 2020). "In studies of lung cancer, it was observed that C57BL/6J mice lacking complement C3 (C3-/- mice) exhibited markedly diminished growth of primary and metastatic tumors." (PMID 39958348, 2025).
Autoimmunity (34 papers, 2011 to 2026). The occurrence of an immune reaction against the organism's own cells or tissues. "Complement C3 is the convergent point of the classic, lectin, and alternative pathways and has been implicated in autoimmunity." (PMID 34613773, 2021). "Deficiency of early components of the classical pathway (C1, C2 and C4) leads to autoimmunity whereas deficiency of C3 and its regulators has been associated with severe recurrent bacterial infections and autoimmunity." (PMID 34362117, 2021). "In contrast, homozygous loss-of-function variants in C3 are usually implicated in C3 deficiency, manifested by increased susceptibility to recurrent bacterial infections and autoimmunity, unrelated to aHUS." (PMID 34248927, 2021). "Deficiencies in C1q or C4 predispose to autoimmunity, while deficiency in C3 affects the suppression of contact sensitization and generation of oral tolerance." (PMID 25039245, 2015). "Reduced C3 levels due to the mutation in this patient could favour the appearance of autoimmunity, not only due to C3 role in self-tolerance development, but also because of defective immune complex clearance caused by hypocomplementemia." (PMID 25886501, 2015). "Therefore, these complement modulating agents may also have a role in treating autoimmunity/autoinflammation associated with GOF C3 mutations via reduction of uncontrolled activation of the alternate complement pathway." (PMID 30443255, 2018). "It should be considered in adolescents and young adults with proteinuria, especially in the setting of positive autoimmune serologies or previously diagnosed autoimmune conditions and biopsy findings of subepithelial deposits with isolated C3 staining." (PMID 40954329, 2026). "retrospectively analyzed 108 patients with various autoimmune conditions, including 8 sJIA patients, and found that 30% experienced C4 reductions and 21% experienced C3 reductions following TCZ therapy." (PMID 40948753, 2025). "The complement system also plays a crucial role in SLE pathogenesis, particularly components such as C1QA, C1QB, C2, and C3, which are essential for clearing apoptotic debris and immune complexes, thereby reducing autoimmunity and systemic inflammation." (PMID 39717551, 2024). "In this study, we aimed to determine the role of complement C3 in the development of a recently described SSc mouse model based on autoimmunity to angiotensin II receptor type 1 (AT1R)." (PMID 39737181, 2024). "We here confirm that C3, and to a lower extent, C4 hypocomplementemia are common features of BSS, and that this pathology is frequently associated with autoimmunity." (PMID 31924231, 2020). "Lastly, potential universal intracellular C3 activation suggests that a deregulation of this system could contribute to other diseases beyond Th1 cell-mediated autoimmunity, including cancer or allergies." (PMID 24315997, 2013). "In accordance with this, our data provide a direct link between CFH and B-cell dependent autoimmunity, as we found that CFH controls splenic C3 cleavage and modulates BCR signaling, thus contributing to physiological B cell development." (PMID 31354740, 2019). "To identify undiagnosed autoimmunity, we perform screening autoantibody testing with antinuclear antibody (ANA) by immunofluorescence, direct and indirect Coombs test (DCT/ICT), C3 level, HbA1c, thyroid function test (TFT) in all patients suspected of having immune dysregulation." (PMID 41142805, 2025). "Whether elevation of C3 and C4 reflects a state of cancer-related chronic inflammation or is partially driven by ICI-related autoimmunity therefore warrants further investigation." (PMID 40506552, 2025). "Based on the positivity of immunoglobulin (Ig) staining, MGPN now are divided into Ig (+) C3 (+)-MPGN such as infection, autoimmune/rheumatological diseases, or monoclonal gammopathy-mediated GN, and Ig (−) but C3 (+)-MPGN including C3 glomerulonephritis (C3GN) and dense-deposit disease (DDD)." (PMID 33553201, 2020).
Autoimmunity (continued). "Compared to the non-LN group, patients in the LN group had higher autoimmunity evidenced by a higher proportion of low C3 and C4 levels, positive anti-double-stranded DNA antibody levels, and lower estimated glomerular filtration rates (eGFR)." (PMID 30640964, 2019). "At this point Donor Specific Antibodies, serum C3 and C4 levels and autoimmunity tests were negative, microalbuminuria/creatininuria ratio was 56.82 mg/g." (PMID 30526503, 2018). "Donor Specific Antibodies, serum C3 and C4 levels and autoimmunity tests were negative." (PMID 30526503, 2018). "Thus, lack of autocrine CD46 activation, such as in CD46- and C3-deficient patients, results in subnormal Th1 cell responses, whereas uncontrolled autocrine C3 activation and dysregulated CD46 engagement contribute to hyperactive Th1 cell responses in autoimmune pathologies." (PMID 26084023, 2015). "Recently, a study from Botto's group suggested that C1q, but not C3, can promote metabolic changes in CD8+ T cells, regulating their function and reducing autoimmunity damage, thereby partially clarifying the discrepancy between C1q and C3 deficiency." (PMID 31037070, 2019).
nephrotic syndrome (34 papers, 2012 to 2026). A collection of symptoms that include severe edema, proteinuria, and hypoalbuminemia; it is indicative of renal dysfunction. "Our present results showed that a low serum C3 level was associated with more severe kidney involvement at diagnosis, as judged from clinical and laboratory data: a greater likelihood of oligoanuria, a peak SCr level ≥500 μmol/L, and nephrotic syndrome." (PMID 37475859, 2023). "The present study confirms that the complement factors C3 and FB of the alternative complement pathway are excreted in the urine after induction of experimental nephrotic syndrome." (PMID 40909784, 2025). "Nephrotic syndrome was found in 33.7% (n=28) of children, reduced C3 level in 84.3% (n=70), and elevated antistreptolysin O titer (ASOT) in 69.9% (n=58)." (PMID 41246678, 2025). "Reduced serum C3 levels; nephritic/nephrotic syndrome.Lobular appearance of the glomerulus with cleavage of the basement membrane and mesangial, subendothelial and subepithelial deposits." (PMID 36835304, 2023). "Serum albumin levels were higher, and the combined nephrotic syndrome clinical score was lower in C3 siRNA-treated mice than control siRNA-treated mice." (PMID 36709213, 2023). "We report the case of a middle-aged male patient presenting with nephritic and nephrotic syndromes and low serum C3, whose biopsy established the diagnosis of C3 glomerulonephritis." (PMID 38213351, 2023). "For this reason, we have excluded patients suffering from nephrotic syndrome to circumvent the chance of detecting blood born C3." (PMID 34767613, 2021). "IgG4-TIN patients presented with renal dysfunction, and 94.3% had low serum complement C3 and IgG4-GN presented with nephrotic syndrome, while renal pelvis and ureter involvement had normal renal function and urinalysis." (PMID 32714995, 2020). "A 76-year-old Chinese man presented with low serum C3 level, haematuria and nephrotic syndrome, and experienced rapid worsening of renal function over a period of 10 months." (PMID 31823738, 2019). "Ten (29%) patients had nephritic syndrome, characterised by a lower C3 (p = 0.003) at baseline than those with nephrotic syndrome; C4 levels were normal." (PMID 29385997, 2018). "The present study described the effects of the C3 deposition in tubular cells of pediatric patients with nephrotic syndrome." (PMID 30003098, 2018). "Nephritic syndrome was characterised by a lower baseline complement C3 than nephrotic syndrome (p = 0.0027)." (PMID 29385997, 2018). "Elevated serum C3 complement was also found in glomerular membranes in patients with cGVHD and nephrotic syndrome, and deposits of C3 were found at the dermal-epidermal junction in skin biopsies of patients with cGVHD and with systemic sclerosis." (PMID 27374828, 2016). "In patients with nephrotic syndrome, serum C3 levels were 97.8±14.7 mg/dl and 6 (15.8%), 25 (65.7%), and 7 (18.4%) patients had mesangial C3 deposits of 0, 1+, and 2+ or more, respectively." (PMID 22792353, 2012). "The reduced proteinuria in C3−/− mice was accompanied by a less severe nephrotic syndrome." (PMID 36709213, 2023). "Clinically, it presents with nephritic syndrome or nephrotic syndrome and reduced serum C3 levels." (PMID 36835304, 2023). "Baseline renal function decline was associated with achieving CR, while nephrotic syndrome, anti-dsDNA antibody, and serum C3 levels were not." (PMID 33452282, 2021). "Therefore, it is conceivable that plasmin might be one of the drivers of C3 activation in nephrotic syndrome, although other proteases capable of activating C3 might act in concert and have been reported to be excreted in nephrotic urine such as thrombin, coagulation factor X or plasma kallikrein." (PMID 40909784, 2025). "These patients had nephrotic syndrome at presentation, had no mesangial hypercellularity or any proliferative lesions, had mild mesangial C3 staining and were classified as having normal glomeruli by LM." (PMID 38658875, 2024).
nephrotic syndrome (continued). "Nilotinib: Nephrotic syndrome (proteinuria; scrotal and lower limb edema).Renal biopsy:○No amyloid, kappa, lambda, C3, or immunoglobulin A or immunoglobulin G deposits.○Minimal changes due to CML and nephrotic syndrome." (PMID 39796721, 2024). "We report a case of a 13-year-old girl diagnosed with DDD at 9 years of age, with nephritic and nephrotic syndrome and C3 nephritic factor-negative alternative complement pathway activation." (PMID 33329990, 2020). "In a recent large retrospective study, a high proportion of patients with simultaneously occurring intraglomerular IgM/C3 deposition failed to achieve remission and had refractory nephrotic syndrome." (PMID 28857521, 2017). "Except for some segmental entrapment, glomeruli were negative for IgG, IgA, IgM, C3, and C1q by direct immunofluorescence (not shown), ruling out the possibility of C1q steroid-resistant nephrotic syndrome." (PMID 28724397, 2017). "We also found that the differences of nephrotic syndrome, proteinuria, activity indices score, cellular crescents, interstitial inflammation cell infiltration, leukocyte infiltration and tubular atrophy, were more significant in PTX3 group than anti-ds-DNA antibody or C3 level groups." (PMID 26817892, 2016). "We continued to track the etiology of nephrotic syndrome, and the child had no family history of renal disease; therefore, we investigated secondary factors, including serology results that were positive for ANA and anti-dsDNA with low C3 levels." (PMID 33203428, 2020). "However, the classification of nephrotic syndrome was due to no history of antecedent infection and low ASOT level, no frank haematuria and normal complement C3 levels." (PMID 29385997, 2018).
asthma (33 papers, 2005 to 2026). "Other studies have identified polymorphisms in complement-encoding genes that correlate with poor outcomes, such as an association between C3 rs448260 and more frequent asthma hospitalizations." (PMID 40309766, 2025). "Among them, 4 genes validated by ROC curve analysis with AUC > 0.70 revealed potential diagnostic values for asthma, including C3, PTGIR, CX3CL1 and PTHLH." (PMID 38640283, 2024). "C3, C5 and their receptors have also been implicated in pathogenesis of asthma, cystic fibrosis, and idiopathic pulmonary fibrosis." (PMID 35672453, 2022). "Many genes, including Il33, Cxcl5, Cxcl15, Ccl20, Cxcl3, Cxcl1, C3, and Pfn1, which have been linked to asthma pathogenesis, showed a cell type-specific response to HDM." (PMID 35627266, 2022). "Some DEGs from this comparison, such as Fos, Jun, Hes1, Cd14, and C3, have been associated with asthma pathogenesis." (PMID 35627266, 2022). "Numerous studies investigating the role of C3 in asthma have shown C3-deficient mice have consistently decreased AHR." (PMID 17044927, 2006). "They prospectively compared the risk of asthma hospitalization between individuals with the highest and the lowest tertile of blood C3 levels and found that high C3 levels are risk factors for asthma hospitalization in the general population and for exacerbation in allergic asthma." (PMID 38892755, 2024). "Additionally, high levels of plasma complement C3 have been linked to an increased risk of asthma hospitalizations and exacerbations in asthmatic patients, suggesting a causal role of the complement system in the development of asthma." (PMID 37996869, 2023). "The C3 rs2230199 (G > C) polymorphism produces a change from arginine to glycine (p.Arg102Gly), giving rise to a missense variant that partially alters the functionality of complement in asthma." (PMID 37108192, 2023). "Additionally, single nucleotide polymorphisms in C3 and C3a receptor genes increases susceptibility to asthma." (PMID 15723703, 2005). "Moreover, C3 protein measured in exhaled breath was associated with uncontrolled asthma." (PMID 40309766, 2025). "At the systemic level, serum C3, C3a, and C4a are elevated and positively correlated with asthma severity outcomes among adults and children." (PMID 40309766, 2025). "Among them, C3, PTGIR, CX3CL1, and PTHLH has important clinical diagnostic value and are correlated with infiltration of multiple immune cell types in asthma." (PMID 38640283, 2024). "Challenge of mice lacking C3 (C3−/−) or C3aR (C3aR−/−) with OVA or other allergens have demonstrated the C3a/C3aR axis as an important contributor of the effector phase of asthma." (PMID 38178176, 2024). "C3, PTGIR, CX3CL1, and PTHLH have important clinical diagnostic values and are correlated with infiltration of multiple immune cell types in asthma." (PMID 38640283, 2024). "Since C3 expression is decreased in asthma, IPF, and MLD, identifying pathways that reduce its expression can be effective in treatment." (PMID 37422662, 2023). "IgG, IgA, tIgE, and C3 levels were lower in the asthmatic bronchitis group than in the asthma children (p < 0.05)." (PMID 37893483, 2023). "The role of the complement system in asthma has previously been described with the main focus on C3 and C5 complexes." (PMID 26292153, 2015). "To gain further insight into the relationship between VEGF and C3 and their effects on CNV in asthma, we investigated the use of compstatin to test the effect of C3 activation in the retina." (PMID 22567103, 2012). "Complement C3 plays a central role as a mediator of airway hyper-responsiveness and asthma, and induces the expression of the Th2 phenotype." (PMID 21211037, 2011). "To further validate our findings, we analyzed the correlation between 4 hub genes (C3, PTGIR, CX3CL1, and PTHLH) and immune cell infiltration in asthma, This result indicates that C3, PTGIR, CX3CL1, and PTHLH expression were significantly correlated with the infiltration of immune cells." (PMID 38640283, 2024).